PTK7 (protein tyrosine kinase 7 (inactive))
Diseases named in the same sentence as PTK7 in open-access papers (continued):
Sharing a sentence is not in itself a finding about the gene and the disease.
esophageal cancer (5 papers, 2017 to 2024). A primary or metastatic malignant neoplasm involving the esophagus. "A paired analysis showed that the PTK7 mRNA level was higher in esophageal cancer tissues than in adjacent normal tissues (P < 0.001)." (PMID 29867084, 2018). "In samples of endometrial, head and neck, lung, ovary, cervical, prostate, breast, pancreatic, bladder, thyroid, and esophageal cancers, the mean PTK7 mRNA levels were higher than the overall mean level from all cancer tissues." (PMID 29867084, 2018). "A further examination in esophageal cancers revealed that PTK7 mRNA level is higher in cancer tissues than that in adjacent normal tissues, and the level is higher in ESCC than that in EAC." (PMID 29867084, 2018). "We analyzed samples comprising a broad range of cancer types in the database from TCGA and found that PTK7 mRNA levels are high in many cancers, including endometrial and esophageal cancers." (PMID 29867084, 2018). "Given the fact that the esophageal cancer biomarkers are scarce for clinical use, our ongoing work on PTK7 has significant implications in the diagnosis and treatment of this cancer." (PMID 28545451, 2017). "Specifically, we evaluated the expression of PTK7 in esophageal cancer by Oncomine expression analysis and validated the observation in clinical tumor samples by immunohistochemistry (IHC) staining of the PTK7 protein." (PMID 28545451, 2017). "The goal of the current study is to investigate the role of PTK7 in the oncogenic progression of esophageal cancer." (PMID 28545451, 2017). "In our previous study analyzing RNA-seq data from TCGA, the mean PTK7 mRNA levels in endometrial, head and neck, lung, ovary, cervical, prostate, breast, pancreatic, bladder, thyroid, and esophageal cancer tissues were higher than the mean PTK7 mRNA levels from all cancer tissues in the database." (PMID 37569547, 2023). "Therefore, based on the results obtained from the in vitro proliferation and invasion assays, we propose that PTK7 positively regulates tumorigenesis and metastasis of esophageal cancer." (PMID 28545451, 2017). "Moreover, studies on PTK7 in gastric and esophageal cancers are also prevalent." (PMID 39474113, 2024). "Therefore, PTK7 may be a promising therapeutic target in esophageal cancer, and its clinical implications should be further demonstrated by extensive and meticulous examination in clinical studies." (PMID 28545451, 2017). "We hypothesize that PTK7 positively regulates tumorigenesis of esophageal cancer." (PMID 28545451, 2017).
head and neck cancer (5 papers, 2019 to 2024). A primary or metastatic malignant neoplasm affecting the head and neck. "The correlation between PTK7 and clinicopathological characteristics of head and neck cancer was also consistent with its correlation with patient prognosis." (PMID 39474113, 2024). "Role of PTK7 in urologic tumor, head and neck cancer, brain tumor, and sarcoma." (PMID 39474113, 2024). "In head and neck cancer, PTK7 mRNA expression was higher in cancer cells than in normal cells, using TCGA data." (PMID 35257502, 2022).
liposarcoma (5 papers, 2014 to 2024). A usually painless malignant tumor that arises from adipose tissue. "PTK7 expression is also reported to be associated with significantly worse 3-year DRFS outcome in liposarcoma patients." (PMID 24409301, 2014). "Data reported in the literature in some other malignancies, including liposarcoma, oesophageal squamous cell carcinoma and invasive cholangiocarcinoma, are also consistent with a similar adverse impact of PTK7 expression on clinical outcome." (PMID 25962058, 2015). "Similarly, Knockdown of PTK7 has been shown to inhibit proliferation and invasion of liposarcoma cells and induces apoptosis." (PMID 24987951, 2014).
non-small cell lung carcinoma (5 papers, 2020 to 2025). A group of at least three distinct histological types of lung cancer, including non-small cell squamous cell carcinoma, adenocarcinoma, and large cell carcinoma. "Clinical trials further confirmed the potential of PTK7-targeting ADCs, showing significant anti-tumor activity in patients with non-small cell lung cancer." (PMID 39936972, 2025).
spina bifida (5 papers, 2014 to 2021). A congenital neural tube defect in which vertebrae are not fully formed. "These previous observations led us to explore a potential association between PTK7 and the risk for human spina bifida." (PMID 30689296, 2019). "DNA resequencing of all 382 subjects (192 spina bifida cases and 190 non‐malformed controls) identified 9 rare missense PTK7 DNA variants (MAF <1%) and five common variants (MAF ≥1%)." (PMID 30689296, 2019). "We identified three rare (MAF <0.001) missense heterozygous PTK7 variants (NM_001270398.1:c.581C>T, p.Arg630Ser and p.Tyr725Phe) in the spina bifida patients." (PMID 30689296, 2019). "Discovery of heterozygous digenic deleterious variants in human NTD cases with spina bifida (i.e. PTK7/ SCRIB) and anencephaly (i.e. CELSR1/SCRIB; CELSR1/DVL3) strongly support the strategy of screening PCP genes to discover risk alleles contributing to human NTDs3,12." (PMID 33574475, 2021). "In human, LoF mutations in PTK7 and the double-heterozygous mutation of PTK7 and VANGL2 were associated with spina bifida and increased the genetic risk of NTDs." (PMID 34828397, 2021). "Actually, in our recently digenic PCP variants screen in 510 NTDs, PTK7, and SCRIB double heterozygous variants were identified in a spina bifida case." (PMID 30689296, 2019). "In this study, we initially sequenced exons of the human PTK7 gene in 192 spina bifida patients and 190 controls from a California population." (PMID 30689296, 2019). "Only spina bifida is found in digenic heterozygotes at Vangl2;Ptk7, Vangl2;Grhl3, Vangl2;Sec24b, and Celsr1;Ptk7." (PMID 30134561, 2018). "We also evaluated the association of common PTK7 SNPs in spina bifida cases and failed to observe any significant frequency differences for the five common SNPs that were detected." (PMID 30689296, 2019). "In mice, Ptk7 heterozygotes did not present with NTDs; while Ptk7 and Vangl2lp double heterozygotes had a distinct spina bifida phenotype." (PMID 30689296, 2019). "To determine whether there are PTK7 and VANGL2 combined rare missense variants in human spina bifida cases, we re‐sequenced VANGL2 in the 192 spina bifida cases used in the current study (data not shown)." (PMID 30689296, 2019). "It was demonstrated in mice that homozygous PCP mutations caused craniochisichisis, as shown for Vangl2, Celsr1, and Ptk7 while double heterozygosity for a PCP mutation and non-PCP mutation can cause spina bifida, as shown for Vangl2/Dact1 double heterozygotes." (PMID 24632739, 2014).
breast tumors (4 papers, 2014 to 2024). "The research presented in this study demonstrates the largest investigation of PTK7 protein expression in primary breast tumours to date, although it is limited to tumours collected at one location within the United Kingdom." (PMID 39335176, 2024). "PTK7 protein expression was evaluated in 1136 early-stage invasive breast tumours by immunohistochemistry." (PMID 39335176, 2024). "We investigated whether PTK7 overexpression in ER-negative BC cell lines also reflects the expression status in ER-negative human breast tumors and LN metastasis." (PMID 24409301, 2014).
glioma (4 papers, 2015 to 2025). A benign or malignant brain and spinal cord tumor that arises from glial cells (astrocytes, oligodendrocytes, ependymal cells). "Higher PTK7 expression was consistent with higher CD44 expression in the mesenchyma-like glioma subtype." (PMID 39474113, 2024). "Mechanistically, PTK7 knockdown attenuates tumor cell proliferation and impairs tumorigenic potential in CD44-high glioma cell lines." (PMID 39474113, 2024). "PTK7 regulates Id1 expression to promote cell proliferation and tumorigenesis, inhibit apoptosis of CD44-high gliomas, and induce anchorage-independent growth of normal astrocytes through the TGF-β/Smad signaling." (PMID 39474113, 2024). "A previous study showed that PTK7 expression was significantly positively correlated with the expression of CD44, a biomarker for the mesenchyma-like glioma subtype." (PMID 39474113, 2024).
lung adenocarcinoma (4 papers, 2021 to 2024). A carcinoma that arises from the lung and is characterized by the presence of malignant glandular epithelial cells. "In lung adenocarcinoma, PTK7 was found to be overexpressed in cancer tissues compared to normal lung tissues, and the positivity of PTK7 expression was higher in cases with ALK mutations and lower in cases with EGFR mutations." (PMID 39474113, 2024). "Another controversial finding was in the field of lung adenocarcinoma, where it was found that PTK7 expression correlates with lymph node metastasis, and that high PTK7 expression implies a higher rate of ALK mutation and a lower rate of EGFR mutation." (PMID 39474113, 2024). "In lung squamous cell carcinoma (LSCC), PTK7 unexpectedly exerts a cancer suppressor role, which is quite different from the role of PTK7 in lung adenocarcinoma and most other cancer types." (PMID 39474113, 2024). "Functional investigation revealed that PTK7 knockdown decreased cell viability and increased apoptosis in lung adenocarcinoma cell lines." (PMID 34475869, 2021). "A recent study revealed that PTK7 expression is associated with EGFR mutations and plays an oncogenic role in lung adenocarcinomas." (PMID 34367983, 2021). "In lung adenocarcinoma and serous ovarian cancer, PTK7 expression also correlated with better OS." (PMID 39474113, 2024). "PTK7 is highly expressed and plays an oncogenic role in lung adenocarcinoma." (PMID 34367983, 2021).
Alzheimer disease (3 papers, 2020 to 2024). A progressive, neurodegenerative disease characterized by loss of function and death of nerve cells in several areas of the brain leading to loss of cognitive function such as memory and language. "The genes represented by the age‐DMRs included a few notable members such as Cyp46a1 and Abca7, which are involved in cholesterol metabolism and implicated in Alzheimer's disease, and few members of the WNT signaling and mesenchyme developmental pathways (e.g., Fzd1, Fzd8, Wnt5a, Jak3, Ptk7, Nrp2)." (PMID 32790008, 2020).
bladder cancer (3 papers, 2022 to 2025). "PTK7 is overexpressed in various malignancies, including bladder cancer, and is therefore a viable therapeutic target." (PMID 40885785, 2025). "In bladder cancer, PTK7 aptamer-Gemcitabine conjugate (PTK7-GEMs) specifically bind to cancer cells dependent on the expression levels of PTK7 and PTK7-GEMs showed more robust anti-tumor efficacy and excellent biosafety in tumor xenograft mice models." (PMID 39474113, 2024). "This study evaluated the preclinical efficacy of [212Pb]Pb-TCMC-chOI-1, a 212Pb-labeled antibody targeting PTK7, for targeted alpha-emitting radionuclide therapy in bladder cancer using 2D adherent cultures (clonogenic assay) and 3D multicellular spheroid models (spheroid growth inhibition)." (PMID 40885785, 2025). "Moreover, PTK7-GEMs treatment resulted in lower tumor stage the majority of the examined bladder cancers (stage pT0/Ta/T1)." (PMID 36471380, 2022).
idiopathic scoliosis (3 papers, 2017 to 2024). A scoliosis with no known cause. "A recent study demonstrated that a targeted mutation in the zebrafish D. rerio ptk7 gene, whose encoded protein functions in cell communication, leads to both congenital and idiopathic scoliosis according to the timing of gene loss of function." (PMID 35853984, 2022). "Ptk7 mutant zebrafish were recently discovered as a model for congenital and idiopathic scoliosis." (PMID 28424771, 2017). "Ptk7 has been known to be an essential regulator for the Wnt-β-catenin and the non-canonical Wnt-PCP signaling pathways, and the ptk7 zebrafish mutant has been used as a model for idiopathic scoliosis." (PMID 39513856, 2024).
lung squamous cell carcinoma (3 papers, 2018 to 2024). "In lung squamous cell carcinoma cells, the overexpression of PTK7 decreases cell proliferation, migration, and invasion by suppressing ERK and Akt phosphorylation." (PMID 29867084, 2018). "Notably, the sample size involved in the analysis of PTK7 expression levels in this study was too small, whereas in the TCGA lung squamous cell carcinoma cohort, PTK7 is upregulated in cancer tissues." (PMID 39474113, 2024).
metastatic tumors (3 papers, 2015 to 2025). "To investigate possible differences between primary and metastatic tumors, we examined additional primary tissues from a small cohort of 7 PTK7-positive liver metastases." (PMID 25962058, 2015).
pancreatic cancer (3 papers, 2023 to 2025). "Sgc8c was chosen for its ability to target PTK7, which is overexpressed in pancreatic cancer, and for being easier to modify than antibodies, thereby enhancing treatment precision and efficacy." (PMID 39397032, 2024). "To validate PTK7 as a target in pancreatic cancer, we conducted survival analysis, comparative expression studies using The Cancer Genome Atlas (TCGA) data, and immunohistochemical (IHC) staining." (PMID 39397032, 2024). "Studies have shown that PTK7 is overexpressed in several types of cancers, including pancreatic cancer, as demonstrated in our flow cytometry results." (PMID 39397032, 2024). "Cells were incubated with Cy5-labeled Lib, Sgc8c, or Sgc8c-MMAE on ice for 30 min, and flow cytometry results highlighted modest PTK7 expression in specific pancreatic cancer subsets." (PMID 39397032, 2024). "While studies have already shown that SERPINH1 is a stromal marker and confers chemoresistance, our study identified PTK7 as a novel marker of fibroblasts in invasive pancreatic carcinomas." (PMID 36587397, 2023). "IHC showed high PTK7 expression in pancreatic cancer tissues across different stages." (PMID 39397032, 2024). "Preliminary analyses indicate that the efficacy of Sgc8c-M appears to depend on PTK7 expression levels in different tumor models of the same cancer type, including TNBC, pancreatic cancer, and NSCLC." (PMID 40987771, 2025). "We propose a specific assay based on PTK7 and SERPINH1 detection by immunohistochemistry to better characterize pancreatic carcinoma invasiveness and prognosis." (PMID 36587397, 2023). "Sgc8c is a biocompatible and non-toxic nucleic acid aptamer that specifically binds to PTK7, a protein overexpressed in pancreatic cancer tissues." (PMID 39397032, 2024).
thyroid cancer (3 papers, 2023 to 2024). "As for thyroid cancer, PTK7 expression is associated with advanced TNM stage and a high frequency of intraglandular dissemination." (PMID 39474113, 2024). "Immunohistochemistry results show abnormal expression of proteins such as FKBP5, CENPF, CX26, KIF11, PTK7, which are associated with poor prognosis in thyroid cancers with intraglandular dissemination, offering potential guidance for specific targeted therapy in the future." (PMID 39135992, 2024). "PTK7 is also highly expressed in human thyroid cancer tissues, and PTK7 knockdown inhibits cell proliferation and promotes cell apoptosis in vitro." (PMID 39474113, 2024). "Thus, PTK7 is involved in the progression of thyroid cancer and holds promise as a new therapeutic target." (PMID 39135992, 2024). "Additionally, cell experiments indicated that PTK7 can promote cell proliferation (thyroid cancer: TPC-1 and KTC-1 cell lines) and inhibit apoptosis, while animal experiments showed that the tumor volume in the PTK7 knockout group was significantly smaller than that in the control group." (PMID 39135992, 2024).
acute leukemia (2 papers, 2017 to 2024). A clonal (malignant) hematopoietic disorder with an acute onset, affecting the bone marrow and the peripheral blood. "Aptamer-based nanodiagnostics systems have been proposed for acute leukemia via an antileukemia-thiolated aptamer (sgc8c) that specifically recognizes protein tyrosine kinase 7 (PTK7), an overexpressed transmembrane receptor in human T-cell ALL cells." (PMID 29326927, 2017). "An antileukemia-thiolated aptamer (sgc8c) that selectively identifies protein tyrosine kinase 7 (PTK7), an overexpressed transmembrane receptor in human T cell ALL cells, has been proposed for use in aptamer-based nanodiagnostics devices for acute leukemia." (PMID 38594732, 2024).
cholangiocarcinoma (2 papers, 2014 to 2015). A carcinoma that arises from the intrahepatic biliary tree (intrahepatic cholangiocarcinoma) or from the junction, or adjacent to the junction, of the right and left hepatic ducts (hilar cholangiocarcinoma). "In cholangiocarcinoma cells, PTK7 depletion affected the level of cell-cycle related proteins, increasing Cdk2, Cdk4, Cdk6, and cyclin D1 and decreasing p16, p21, and p27, whereas it increased mitochondrial-dependent apoptosis." (PMID 25962058, 2015). "Firstly, six human cholangiocarcinoma cell lines (HuCCT1, SCK, JCK, Cho-CK, Choi-CK, and OZ) were tested with the PTK7 antibody." (PMID 24587299, 2014).
clear cell renal carcinoma (2 papers, 2021 to 2024). A malignant epithelial neoplasm of the kidney characterized by the presence of lipid-containing clear cells within a vascular network. "In clear cell renal carcinoma (ccRCC), PTK7 expression was shown to be dowregulated, which is different from the changes in PTK7 expression in most solid tumors." (PMID 39474113, 2024).
esophageal tumors (2 papers, 2017 to 2021). "Both Oncomine expression analysis and clinical tumor IHC confirmed that PTK7 is upregulated in esophageal tumors." (PMID 28545451, 2017).
medulloblastoma (2 papers, 2017 to 2024). A malignant, invasive embryonal neoplasm arising from the cerebellum. "In medulloblastoma, PTK7 expression is also upregulated in tumor tissues." (PMID 39474113, 2024). "Furthermore, microarray analysis of human medulloblastoma patient tumors indicate significant upregulation of key targets in the Hedgehog signaling pathway and Protein Tyrosine Kinase (PTK7)." (PMID 29099739, 2017). "Thus, it is reasonable to speculate that PTK7 may also play important roles in medulloblastoma tumorigenesis." (PMID 39474113, 2024). "In this brief report, following an analysis of microarrays of medulloblastoma patients, we identify key proteins—such as LSD1, EZH2, GLI2, GLI3, and PTK7—that may serve as drug targets." (PMID 29099739, 2017).
oral squamous cell carcinoma (2 papers, 2022 to 2024). "In oral squamous cell carcinoma, higher PTK7 expression implies not only a later TNM stage, more lymph node metastasis, and poorer differentiation, but also a higher risk of YK classification." (PMID 39474113, 2024). "The purpose of this study was to evaluate the association between the immunohistochemistry (IHC) of protein tyrosine kinase 7 (PTK7) expression and clinicopathological factors of oral squamous cell carcinoma (OSCC)." (PMID 35257502, 2022). "In oral squamous cell carcinoma, the expression level of PTK7 was significantly upregulated." (PMID 39474113, 2024).
adenoma (1 paper, 2019). A neoplasm arising from the epithelium. "Moreover, overexpression of PTK7 has been implicated as a biomarker for adenoma and CRC, and is correlated with several clinicopathological features such as TNM stage, tumor differentiation, lymph node and distant metastasis." (PMID 30952955, 2019).